CD27 (CD27 molecule)
Diseases named in the same sentence as CD27 in open-access papers (continued):
Sharing a sentence is not in itself a finding about the gene and the disease.
tumor (continued). "CDX-527 induced ADCC in tumor cell lines endogenously expressing PD-L1 or CD27, or cells transfected with the receptors, though the BsAb was somewhat less potent than the parental 2B3 mAb with the CD27 expressing cells." (PMID 32451681, 2020). "Moreover, we found an inverse correlation of CD8(+)/CD57(+) and CD27(−) T cell fractions with benign internal tumor load." (PMID 32193699, 2020). "Loss of CD27/CD28, which has been described as a hallmark of ageing, could be partially responsible for decreased tumor infiltration by CD8+ cells observed in the older patients of our cohort." (PMID 33024560, 2020). "The higher expression of CD27 was a favorable prognostic marker and associated with good survival outcomes in multiple cancers like CESC, HNSC, LIHC and SKCM after adjusting for the abundances of tumor infiltrating immune cells." (PMID 31358815, 2019). "CD70 and CD27 expression was demonstrated in a broad range of tumour types." (PMID 31652572, 2019). "CD27 is expressed not only on activated lymphocytes but also on tumor cells." (PMID 31624593, 2019). "However, L-selectin controls other aspects of T cell activation as shown by increased numbers of CD44+ CD27+ “central memory” F5LΔP cells in the lungs of tumor bearing mice as well as Ki67 expression and altered proliferation ex vivo." (PMID 31249570, 2019). "In addition, many of the haematological malignancies also co-express CD27 on the tumour cells, which enhances tumour cell proliferation and survival." (PMID 31652572, 2019). "All of the subsets showed CD27 positivity (>10% CD27 positive tumour cells)." (PMID 31652572, 2019). "These plus the RNAi data supported that CD27 may suppress the tumor progression or TME development in some types of cancers." (PMID 31358815, 2019). "The tumor microenvironment provides favorable conditions for the enrichment of IL‐17‐producing γδ T cells, notably through enhanced levels of the cytokines IL‐1β, IL‐6, IL‐23 and IL‐7, which favor CD27− γδ T‐cell survival and promote IL‐17 expression." (PMID 31624593, 2019). "Analysis of the same populations in muMt−/− tumor-bearing mice showed a significant increase in the late intermediately mature splenic NK cell population, CD27+CD11b+, between the control wild-type and muMt−/−, and the ranitidine-treated wild-type and muMt−/− mice." (PMID 30158936, 2018). "Our recent preclinical data support the combination of a CD27 agonist with a tumour-targeting mAb." (PMID 30413184, 2018). "Indeed, two injections of 4-1BB or CD27 costimulated NKG2D CAR T cells exhibited in vivo anti-tumor effects in a highly invasive MDA-MB-231 xenograft model of human TNBC, compared to the first-generation NKG2D CAR T cells." (PMID 29980239, 2018). "The increased percentage of B cells in tumor may be a consequence of an increased number of CD27+CD38+/− B cells." (PMID 30774636, 2018). "Confirmation of enhanced B-cell depletion and increased infiltration of myeloid cells with the addition of varlilumab to rituximab, as observed in our preclinical data, will provide a proof of principle that CD27 agonism does indeed enhance the efficacy of tumour-targeting mAbs." (PMID 30413184, 2018). "Anti-CD27 alone also improved survival of tumor-bearing mice, particularly in the A31 model." (PMID 29198913, 2017). "Assessment of expression of genes encoding the TNF receptor superfamily members as well as the immunoglobulin receptor superfamily revealed upregulation of genes encoding CD28, ICOS, 4-1BB, GITR, OX40, CD27 and CD40 within the NDV-injected tumours, with ICOS being most prominent." (PMID 28194010, 2017). "The rationale is, in addition to targeting the GPNMB+ cells with the antibody-coupled to the toxin, the anti-PD-1 antibodies suppress the tumor-promoted inhibition of the antitumor immune response, while the anti-CD27 triggers an activation of the cytotoxic T lymphocytes (CTL)." (PMID 29312320, 2017).
tumor (continued). "In addition, CD70 seems to be involved in the recruitment of CD27-positive Tregs to the TME thus allowing tumor evasion." (PMID 29387053, 2017). "Moreover, anti-CD70 antibodies are considered as promising antibodies to treat human malignancies, inducing apoptosis via CD27 interaction and used to deliver drugs into the tumor." (PMID 26828592, 2016). "In addition, tumor-infiltrating CD3+CD56+ NKT-like cells express low levels of CD45RA but intermediate level of CD27, suggesting that these cells were CD45RA−CD27+/− central/effector-memory cells." (PMID 27409423, 2016). "The Teff:Treg ratio in the tumor has been suggested to determine whether CD27 agonist will promote or diminish tumor control." (PMID 27656185, 2016). "However, the expression of CD27 on regulatory T cells requires further examination to elucidate its role in anti-tumor immune responses in NSCLC." (PMID 25951351, 2015). "CD70 and CD27 expression in the tumor microenvironment was analyzed in 42 primary NSCLC samples." (PMID 25951351, 2015). "As a result, suppression of the anti-tumor response might easily be established through binding of CD70+ cells to CD27+ Tregs, leading to a new immune escape mechanism in NSCLC." (PMID 25951351, 2015). "CD27 triggering may also lead to tumor progression through the recruitment of CD27+ Tregs, complicating the use of CD27 as a target for immunotherapy." (PMID 26605342, 2015). "In addition, we have demonstrated the expression of the CD70 receptor, CD27, in the microenvironment of the tumor and the presence of soluble CD27 in NSCLC patient sera." (PMID 25951351, 2015). "In addition, we have shown the presence of its receptor, CD27, on TILs in the microenvironment of the tumor." (PMID 25951351, 2015). "Moreover, in vivo experiments demonstrated evasion of immune surveillance by recruitment of CD27+ Treg to the tumor site." (PMID 26605342, 2015). "A possible explanation for such variability may be the lack of expression of the conventional B cell markers on the surface of tumor cells, the use of CD27 and IgD to sort PGC and ME sub-populations, or a possible cross-contamination during the flow-sorting." (PMID 26325507, 2015). "Ligation of CD27, for example, primarily results in development of T-cell memory, which could potentially lead to long-term tumor control." (PMID 26317902, 2015). "Moreover, CD27-expressing tumor infiltrating lymphocytes were found adjacent to the tumor cells, suggesting active CD70-mediated signaling." (PMID 25951351, 2015). "The effects of CD27 pathway triggering may depend upon the environment in which the stimulus is delivered—within the tumor microenvironment or in peripheral lymphoid tissues—as well as length of exposure to stimulating agents." (PMID 24855562, 2014). "In this setting, Tregs were critical mediators of CD27-dependent effects on tumor growth." (PMID 24855562, 2014). "Furthermore, wild-type mice treated with an anti-CD27 blocking antibody had fewer Tregs and slower tumor growth than untreated mice." (PMID 24855562, 2014). "There is evidence that the frequency of T cells expressing CD27 increases gradually after ACT and may be associated with the long-term maintenance of a stable number of tumor-specific T cells in responding patients." (PMID 24497917, 2014). "Though it is not yet clear what the optimal combination and arrangement of additional intracellular signaling domains, such as 41BB or CD27 may be, the ability to successfully target tumor cell lines with variety CSPG4-directed CARs is promising." (PMID 25197555, 2014). "In addition to its tumor-restricted expression pattern research has focused on the potential reactivation of antitumor T-cell immunity by agonistic CD27-targeted therapy." (PMID 23840967, 2013). "For instance, upon inclusion in, for example, tumor vaccination strategies, where a de novo antitumor T-cell response is induced, adjuvant use of a CD27 agonist may help optimize T-cell responses." (PMID 23840967, 2013).
tumor (continued). "However, a recent study identified that in established tumor models, CD27 signaling actually promoted tumor growth, with a reduction in Treg apoptosis and production of the Treg survival cytokine IL-2 by CD4+ effector T cells (TEff)." (PMID 23840967, 2013). "Two GZMK+ clusters, GZMK+ early-activation CD8 T cells and GZMK+ late-activation CD8 T cells, are also clonal, tumor-associated, and exhibit signatures that resemble an intermediate stage between activation and exhaustion, reflected by their intermediate level of TCF7 and CD27 expression." (PMID 40610460, 2025). "Additionally, the presence of CD27+ memory B cells may enhance the recruitment of Tregs and MDSCs, further dampening the immune response against the tumor 50-52." (PMID 40657381, 2025). "In addition, we also found that the anti‐TCR‐γδ antibodies staining in spleen sections showed more positive cells in the GCP‐treated group, and the number of tumor‐infiltrated CD27+γδT cells increased significantly in the GCP‐treated group compared to the Model group." (PMID 38604998, 2024). "Thus, CD27 emerges as a crucial regulatory molecule within the tumor microenvironment (TME)." (PMID 38504180, 2024). "Many downregulated genes in tumour‐infiltrating peripheral CD8+ T cells are associated with classical IFN responses (IFI6, IFI27, MX1, STAT1, EPSTI1 PARP9, ISG15), cell proliferation (STMN1, CENPF, HELLS, NUSAP1, and DNPH1), and T cell costimulation (CD28, TMIGD2, TNFRSF4, CD27, and TNFRSF18)." (PMID 39350478, 2024). "Under the Emut VAX treatment, the proportion of the cytotoxic CD27-CD11b+ NK cells increased significantly while that of the pre-mature CD27+CD11b- NK cells decreased, suggesting the involvement of the cytotoxic NK cells in the anti-tumor function of the Emut VAX." (PMID 36875137, 2023). "Therefore, it will be important to study the specific effects of CD27 co-stimulation on Tregs in the context of restricted co-stimulation to a tumor antigen such as EGFR in relevant murine models and in combination with Treg depleting strategies, including sorafenib treatment." (PMID 37545491, 2023). "How CD27− γδ T cells react to tumor-derived factors beyond IL-17A is largely unknown." (PMID 36480166, 2023). "Moreover, CD27 agonism also enhances NK cell activation and proliferation, suggesting that these two additional anti-tumor mechanisms could also be explored in the context of CD27xEGFR treatment in follow-up studies." (PMID 37545491, 2023). "The relevance of CD27 engagement on Tregs in vivo in more physiological conditions remains to be determined, but is suggested by a recent study demonstrating, that CD27 expression on Tregs was necessary to maintain tolerance and to suppress immune responses to tumours." (PMID 36993956, 2023). "Taking together, we found that the expression of CD27 in the stroma, but not in the tumor, might be associated with a better prognosis in patients with HNSCC." (PMID 37153589, 2023). "However, depletion of FoxP3.Luci-DTR Tregs from FoxP3.Luci-DTR + CD27 − / − chimeras by DT injection resulted in a significant reduction in tumor growth and prolonged survival, indicating that CD27 expression on regulatory T cell inhibits immune responses against MC38 tumor cells." (PMID 34423375, 2022). "Abrogation of CD27 expression on Tregs showed synergistically enhanced anti-tumor immunity unleashed by PD-1 blockade, suggesting that targeting Treg-expressed CD27 might be a promising therapeutic strategy to enhance the efficiency of checkpoint inhibition therapy." (PMID 34423375, 2022). "Moreover, conditioning treatment with CD27 mAb in a preclinical model enhanced the expansion and anti-tumor activity of adoptively transferred T cells and by activating T cells recruits and stimulates myeloid cells for enhanced killing of CD27 mAb-opsonized tumors." (PMID 36700229, 2022).
tumor (continued). "Furthermore, a strong correlation between the expressions of CD20 and CD27 (r= 0.752, p<0.001) and Bcl2 (r= 0.734, p<0.001) was found in tumor areas of long-term survivors, which may reflect a specific subtype of B cells like memory B cells." (PMID 36685537, 2022). "It was reported that augmenting CD27 co-stimulation may assist in anti-tumor immunity." (PMID 36467089, 2022). "However, activation of the CD27/CD70 axis may also lead to tumor immunosuppressive effects by enhancing the survival of natural Tregs and inducing the apoptosis of effector T cells." (PMID 35647204, 2022). "Similarly, a comprehensive characterization of immune cells from triple-negative breast cancer patients using paired single-cell RNA and TCR/BCR sequencing revealed that tumor-infiltrating B cells were mostly CD27+ memory B cells and had higher clonality, CSR and SHM than those in the blood." (PMID 34164398, 2021). "Additionally, high expression of CD27 on these γδ T cells is important in determining the role that they could have in promoting tumor progression." (PMID 33282892, 2020). "Instead, it could reflect increased retention due to higher CD69 expression and possibly increased frequency of central memory CD44+ CD27+ T cells at the tumor site which are known to be more efficacious in mouse models of ACT, as found in the disseminated tumor model." (PMID 31249570, 2019). "Moreover, consistent with the fact that IFN-γ+ cells, CD4+, and CD8+ T cells are not affected by neutrophil depletion in vivo, we found that neutrophils from tumor-bearing mice preferentially impacted the in vitro proliferation of CD27− γδ T cells when compared to CD27+ γδ, CD4+, and CD8+ T cells." (PMID 29750788, 2018). "Within the tumours of treated animals, CTLA-4 blockade gave rise to a significantly altered expression of markers associated with dysfunction (PD-1, Lag-3 and CD160), activation (CD25, GITR and CD38), as well as co-stimulation and development (CD27 and CD127) on mLama4-specific T cells." (PMID 28916749, 2017). "Thus, the therapeutic efficacy of anti-CD20/CD27 therapy requires either T or NK cells to augment tumor control by anti-CD20 by a hitherto unknown mechanism." (PMID 29198913, 2017). "However the presence of CD27+ TILs did not appear to be associated with CD70 expression in the tumor cells." (PMID 25951351, 2015). "Thus, activation of human CD27 (TNFRSF7) with a monoclonal antibody (varlilumab) has previously been demonstrated to result in T cell activation and anti-tumor activity in preclinical models, and is currently in early phase clinical trials in patients with advanced malignancies." (PMID 26500773, 2015). "Indeed, ζ and CD27 have been demonstrated to cooperate to mediate enhanced anti-tumor activity." (PMID 23667569, 2013). "Of note, incorporation of CD27 in a bispecific antibody format with a tumor-specific targeting antibody fragment may open up ways to ensure selective modulation and/or inhibition of CD27 signaling in the tumor micro-environment." (PMID 23840967, 2013). "Functional inhibition of CD70/CD27 signaling, achieved either by generating CD70-knockout primary MM cells or with blocking monoclonal antibodies, completely abrogated tumor growth in xenotransplantation models." (PMID 41872502, 2026). "For example, IL-15 provided a less differentiated phenotype, with higher CD27 and CD28 expression, improving in vivo persistence and anti-tumor immunity in tumor-bearing hosts." (PMID 41346587, 2025). "For instance, CD27-based CAR T cells have demonstrated higher antitumor activity and increased survival in tumor-bearing mouse models, upregulating IL-7Rα expression while downregulating PD-1 expression." (PMID 40181405, 2025). "This aberrant CD70/CD27 interaction contributes to immune evasion by influencing the tumor microenvironment (TME) and promoting tumor progression." (PMID 40484866, 2025).
tumor (continued). "Significantly, SAg-exposure enhanced inflammatory activation of CLL tumour cells, which acquired CD38, CD40, CD86, while downregulating CD27 (p≤0.005), even in cultures from ibrutinib-treated CLL patients." (PMID 40207214, 2025). "This unique tumor cluster exhibited high gene expression of 22 genes, including immune checkpoint regulators, like CTLA4, TIGIT, LAG3, and CD27, immune cell surface markers, and inflammatory genes." (PMID 40492347, 2025). "Following 48 h of tumor stimulation, stemness-related genes were generally downregulated; however, SELL and CD27 expression in 4KO-LLT1 CAR-T cells remained almost twice as high as in 4KO CAR-T cells." (PMID 39856752, 2025). "In tumor cells, CD70 engages with CD27, resulting in secretion of soluble CD27 (sCD27) and proteolytic shedding of the CD27 ectodomain." (PMID 40597436, 2025). "In hematological malignancies, tumor cells co-expressing CD27 and CD70 evade immune surveillance within the tumor microenvironment, thereby promoting disease progression." (PMID 40896423, 2025). "In this last study, we found a strong interaction between tumor cells expressing CD70 and T lymphocytes expressing CD27." (PMID 40148586, 2025). "In this retrospective study, we analyzed 190 surgically resected SCLC tumor samples using immunohistochemistry (IHC) for CD70 and CD27 expression and RNAscope for CD70 RNA detection." (PMID 40205178, 2025). "Lastly, while our data suggested a role for CD70-CD27 interaction in MCL progression, further functional studies, such as co-culturing CD70+ tumor cells with CD27+ T cells along with blockade or stimulation, are needed to validate its mechanistic relevance." (PMID 40876452, 2025). "Based on Panel 2 (CD27, CD138, IgG, and CK19) mIF staining, plasma cells and tumor cells were defined as IgG+ plasma cells (CD138+, CD27+/–, IgG+); IgG− plasma cells (CD138+, CD27+/–, IgG−); IgG+ tumor cells (CK19+, IgG+); and IgG− tumor cells (CK19+, IgG−)." (PMID 41008793, 2025). "Previous studies consistently reported that the expressions of LAG-3, PD-1, PD-L1, CD28, CD80, CD27 and CTLA-4 were relevant to the immunosuppression in the tumor microenvironment." (PMID 39781354, 2025). "After treatment, the TCRbhiPD‐1hiCD69+CD27+ CD8+ Teff decreased in proportion in the HB group, while the proportion of Ly6ChiTCRb+CD69+CD27+CD62L+ CD8+ Tcm increased, underscoring the enhanced ability of the immune system to effectively eradicate tumor cells." (PMID 39135526, 2024). "We observed that mIFN-α treatment partially reversed YY1-mediated tumor growth and drug resistance by increasing the expression of CD8 and CD27, markers of T cell activation, in GC tissues." (PMID 38347631, 2024). "Tumor-specific T cells highly expressed CD27, IFNG, GZMB and CXCL13 and secreted more effector cytokines for tumor cell killing, as validated experimentally." (PMID 39033098, 2024). "On day 15 post cancer cell injection, 2 days after the 2nd administration of T cells, tumor size increased to above 75% from baseline for ~80% of mice in PBS-, CD8+ T-cell-, and CD27+Ly6C− γδ T-cell-treated groups." (PMID 38816652, 2024). "Conversely, C11, featured by Ly6ChiTCRb+CD69+CD27+CD62L+, represented a subset of CD8+ Tcm lymphocytes with potential tumor‐killing characteristics." (PMID 39135526, 2024). "The positive rate of CD4, CD45RO, and CD68 was higher, while the positive rate of CD20, CD27 and CD8 was lower in tumor tissues than those in corresponding non tumor tissues, which was coincident with the result of immune infiltration analysis." (PMID 38532632, 2024). "On the other hand, we found that in the pCR group, stimulatory molecules CD27 and CD40L were upregulated, enhancing the anti-tumor activities of T cells." (PMID 39334513, 2024). "In PM1, CD226 was expressed in CD27+ CD4+ and CD4+ Memory subpopulations, and corresponding ligands in tumor cells were TIGB2, NECTIN2 and PVR." (PMID 38528036, 2024).